RNU7-59P (RNA, U7 small nuclear 59 pseudogene)
Synonyms: U7.59
Gene: Small nuclear RNA gene on chromosome 11 (77,566,934 to 77,566,994, reverse strand). Ensembl gene ENSG00000238880.
Homologues: Orthologues: chimpanzee U7 (98% identical), macaque U7 (97% identical). Paralogues in human: RNU7-11P (87% identical), RNU7-80P (87% identical), RNU7-26P (85% identical), RNU7-2P (85% identical), RNU7-34P (85% identical), RNU7-79P (85% identical), RNU7-1 (84% identical), RNU7-13P (84% identical), RNU7-172P (84% identical), RNU7-27P (84% identical), RNU7-57P (84% identical), RNU7-84P (84% identical), and 143 more.